LINC02672 (long independently transcribed non-coding RNA 2672)
Synonyms: OIN1
Gene: Long non-coding RNA gene on chromosome 10 (52,972,612 to 53,030,116, reverse strand). Ensembl gene ENSG00000227121.
Diseases named in the same sentence as LINC02672 in open-access papers:
LINC02672 is named in the same sentence as 2 diseases in open-access papers, as found by Europe PMC text mining. Sharing a sentence is not in itself a finding about the gene and the disease.
LINC02672 shares sentences with these, for which no sentence is quoted: ovarian carcinoma (4 papers); tumor (2).